HLA-DPB1 (major histocompatibility complex, class II, DP beta 1)
Description:
Binds peptides derived from antigens that access the endocytic route of antigen presenting cells (APC) and presents them on the cell surface for recognition by the CD4 T-cells. The peptide binding cleft accommodates peptides of 10-30 residues. The peptides presented by MHC class II molecules are generated mostly by degradation of proteins that access the endocytic route, where they are processed by lysosomal proteases and other hydrolases. Exogenous antigens that have been endocytosed by the APC are thus readily available for presentation via MHC II molecules, and for this reason this antigen presentation pathway is usually referred to as exogenous. As membrane proteins on their way to degradation in lysosomes as part of their normal turn-over are also contained in the endosomal/lysosomal compartments, exogenous antigens must compete with those derived from endogenous components. Autophagy is also a source of endogenous peptides, autophagosomes constitutively fuse with MHC class II loading compartments. In addition to APCs, other cells of the gastrointestinal tract, such as epithelial cells, express MHC class II molecules and CD74 and act as APCs, which is an unusual trait of the GI tract. To produce a MHC class II molecule that presents an antigen, three MHC class II molecules (heterodimers of an alpha and a beta chain) associate with a CD74 trimer in the ER to form a heterononamer. Soon after the entry of this complex into the endosomal/lysosomal system where antigen processing occurs, CD74 undergoes a sequential degradation by various proteases, including CTSS and CTSL, leaving a small fragment termed CLIP (class-II-associated invariant chain peptide). The removal of CLIP is facilitated by HLA-DM via direct binding to the alpha-beta-CLIP complex so that CLIP is released. HLA-DM stabilizes MHC class II molecules until primary high affinity antigenic peptides are bound. The MHC II molecule bound to a peptide is then transported to the cell membrane surface. In B-cells, the interaction between HLA-DM and MHC class II molecules is regulated by HLA-DO. Primary dendritic cells (DCs) also to express HLA-DO. Lysosomal microenvironment has been implicated in the regulation of antigen loading into MHC II molecules, increased acidification produces increased proteolysis and efficient peptide loading.
Synonyms: HLA-DP1B; DPB1; HLA-DP; HLA-DPB
Tractability: Small molecule: a structure with a bound ligand is known. Antibody: its Gene Ontology location is reachable by antibodies, with high confidence; UniProt places it where antibodies can reach, with medium confidence; UniProt predicts a signal peptide or a membrane-spanning region.
Safety:
Unwanted effects reported when the protein is acted on. In parentheses: how it was acted on, where the effect was seen, and who reports it.
asthma (source: ClinPGx)
liver injury (source: ClinPGx)
Gene: Protein-coding gene on chromosome 6 (33,073,786 to 33,089,696, forward strand). Ensembl gene ENSG00000223865.
Subcellular location: Cell membrane; Endoplasmic reticulum membrane; Golgi apparatus, trans-Golgi network membrane; Endosome membrane; Lysosome membrane
Subcellular location (Human Protein Atlas): Cell Junctions; Nucleoplasm
Pathways (Reactome):
Immune System: Co-inhibition by PD-1; Downstream TCR signaling; Generation of second messenger molecules; Interferon gamma signaling; MHC class II antigen presentation; Phosphorylation of CD3 and TCR zeta chains; Translocation of ZAP-70 to Immunological synapse
Gene Ontology:
Molecular function: peptide antigen binding; protein binding; MHC class II protein complex binding
Biological process: antigen processing and presentation of exogenous peptide antigen via MHC class II; positive regulation of T cell activation; positive regulation of T cell proliferation; positive regulation of type II interferon production; T cell receptor signaling pathway; peptide antigen assembly with MHC class II protein complex; positive regulation of immune response; antigen processing and presentation; immune response
Cellular component: cell junction; cell surface; membrane; MHC class II protein complex; clathrin-coated endocytic vesicle membrane; endocytic vesicle membrane; ER to Golgi transport vesicle membrane; Golgi membrane; late endosome membrane; lumenal side of endoplasmic reticulum membrane; lysosomal membrane; plasma membrane; trans-Golgi network membrane; transport vesicle membrane; endoplasmic reticulum membrane; endosome membrane; Golgi apparatus
Genetic constraint (gnomAD): Loss-of-function variants: 29 observed, 26.84 expected, observed/expected ratio (o/e) 1.08, 90% interval 0.8 to 1.47. The upper end of that interval is the gene's LOEUF score, 1.47, which puts it in group 6 of 6, group 1 being the genes least tolerant of losing a copy. Missense variants: 256 observed, 310.24 expected, observed/expected ratio (o/e) 0.83, 90% interval 0.74 to 0.92. Synonymous variants: 112 observed, 128.54 expected, observed/expected ratio (o/e) 0.87, 90% interval 0.75 to 1.02.
Homologues: Orthologues: chimpanzee HLA-DPB1 (96% identical), rabbit HLA-DPB1 (70% identical), rat RT1-Hb-ps1 (57% identical). Paralogues in human: HLA-DRB1 (63% identical), HLA-DQB1 (62% identical), HLA-DQB2 (61% identical), HLA-DRB5 (60% identical), HLA-DOB (53% identical), HLA-DOA (24% identical), HLA-DQA1 (22% identical), HLA-DPA1 (21% identical), HLA-DMB (21% identical), HLA-DQA2 (20% identical), HLA-DRA (20% identical), HLA-DMA (18% identical), and 1 more.
Diseases named in the same sentence as HLA-DPB1 in open-access papers:
HLA-DPB1 is named in the same sentence as 188 diseases in open-access papers, as found by Europe PMC text mining. Sharing a sentence is not in itself a finding about the gene and the disease. The quoted sentences say what the papers report.
COVID-19 (20 papers, 2021 to 2025). A disease caused by infection with severe acute respiratory syndrome coronavirus 2. "Our cohort comprised 48 individuals who had recovered from COVID-19, with 30 (66.7% of 45) being HLA-DPB1*04:01 positive; and 17 (36.2% of 47) carrying HLA-DRB1*15:01." (PMID 41034205, 2025). "Specifically, the HLA-DPB1*04-restricted S167-180 epitope has been shown to stimulate Tfh differentiation, leading to a sustained and robust response to COVID-19 mRNA vaccines." (PMID 39257586, 2024). "Seven of our significant genes higher (GALNT14, OAS1, CCRL2, OAS3, CCR1, OAS2, SIPA1L2) in COVID-19 and two lower (HLA-DPB1, HLA-DQA2) were identified to overlap." (PMID 34335605, 2021). "There was also significant upregulation of MHC-II expression (HLA-DRB5, HLA-DQB2, HLA-DPB1, etc.) in mild COVID-19 patients." (PMID 33473155, 2021). "Nasal macrophages had several differentially expressed (DE) genes in patients with COVID-19 versus patients with LRTD that mirrored alveolar macrophage responses (SPP1, LGALS1 and TMSB10), including IFN-γ response genes (HLA-DPB1, HLA-DQA1 and C1QB)." (PMID 39567718, 2024). "In contrast, expression of MHC-II genes (HLA-DQB1, HLA-DPB1 and HLA-DQA1, etc.)were decreased in COVID-19 acute necrotizing encephalopathy patients, indicating an immune paralysis of T cells." (PMID 37848421, 2023). "Subpopulations of Mono_FCGR3A (CD16 monocytes expressing FCGR3A), Mono_HLA-DPB1, and Mono_HLA-DQA1 were depleted in patients with COVID-19-induced ARDS." (PMID 37363730, 2023). "Differential expression analysis in the scRNA-seq revealed that MHC class II genes, such as HLA-DRB5, HLA-DPB1, HLA-DPA1, HLA-DRB1, and HLA-DRA, were downregulated in convalescent COVID-19 individuals." (PMID 35464396, 2022). "Patients with COVID-19 showed downregulation of genes involved in the AP-1 transcription factor pathway (including JUN, JUNB, JUND, and FOSB) as well as HLA genes (including HLA-E, HLA-DRB1, HLA-DRA, and HLA-DPB1)." (PMID 36992700, 2023). "In contrast to COVID-19(+) TV, highly expressed in the COVID-19(-) PU control group included MHC class II antigen processing (HLA-DRB3/4, HLA-DPB1, HLA-DRA, CIITA, and CD74), mast cell degranulation (TPSAB1/B2), B cell activation (CXCL13, BLNK, IL-6) and histone modification (USP21, HIST1H4E)." (PMID 37026002, 2023). "Further, we investigated the expression of MHC class II molecules (MHCII) and Fc receptors (FcRs) and found that they were broadly upregulated in APCs in lungs of mild COVID-19 patients, with a MHCII subset (HLA-DRA, HLA-DMB, HLA-DRB1, HLA-DPB1, HLA-DQB1, HLA-DMA) were downregulated." (PMID 34502134, 2021). "The dominant S166–180-specific TCRα clonotypes in HLA-DPB1*04:01+ individuals are associated with mild COVID-19 disease, while the dominant S751–765-specific or S866–880-specific TCRα clonotypes in HLA-DRB1*15:01+ participants are associated with non-hospitalised COVID-19." (PMID 41034205, 2025).
autoimmune disease (14 papers, 2017 to 2024). A disorder resulting from loss of function or tissue destruction of an organ or multiple organs, arising from humoral or cellular immune responses of the individual to their own tissue constituents. "The role of the HLA-DPB1 has gained greater relevance due to its association with various pathologies, including cancer, autoimmune diseases, such as rheumatoid arthritis, responses to viral infection, and vaccines." (PMID 36700199, 2022). "Genetic variants in HLA-DPB1 are associated with various autoimmune diseases, including rheumatoid arthritis, Graves' disease, and multiple sclerosis." (PMID 35711523, 2022). "In a wider context, the HLA-DPB1*04:01 variant was suggested as protective also in other autoimmune diseases, such as celiac disease." (PMID 35661780, 2022). "Polymorphisms in promoters in HLA-DPB1 have been associated with autoimmune disease such as systemic sclerosis." (PMID 34211458, 2021). "Several recent studies have examined associations between HLA-DPB1 rs9277535 polymorphism and risk of autoimmune diseases." (PMID 33875616, 2021). "The role of HLA-DPB1 alleles has been studied in a range of other autoimmune diseases, especially NMOSD." (PMID 32560041, 2020). "Several studies have consistently shown that the HLA-DPB1*05:01 allele is associated with an increased risk of various autoimmune diseases, such as rheumatoid arthritis, systemic lupus erythematosus, aplastic anemia, and systemic sclerosis, particularly within the Asian population." (PMID 38540337, 2024). "The HLA-DPB1 rs9277535 polymorphism may play a similar role in RA angiogenesis as that observed for other autoimmune diseases." (PMID 33875616, 2021).
rheumatoid arthritis (14 papers, 2017 to 2024). A chronic, systemic autoimmune disorder characterized by inflammation in the synovial membranes and articular surfaces. "The human leukocyte antigen DPB1 (HLA-DPB1) allele has been shown to influence the susceptibility and severity of rheumatoid arthritis." (PMID 36422613, 2022). "The associations between HLA-DPB1 rs9277535 polymorphism and clinical characteristics of rheumatoid arthritis." (PMID 33875616, 2021). "Logistic regression analysis of associations between HLA-DPB1 polymorphism and risk of rheumatoid arthritis." (PMID 33875616, 2021). "The most significant association was observed between the expression of HLA-DPB1 and rheumatoid arthritis (p = 2.96E-45 in “cerebellum”)." (PMID 31628418, 2021). "HLA-DPB1 is strongly associated with lymphomagenesis and is associated with rheumatoid arthritis." (PMID 36712973, 2022). "Stratified analyses between HLA-DPB1 rs9277535 polymorphism and the risk of rheumatoid arthritis." (PMID 33875616, 2021). "We used a custom-by-design 48-Plex single nucleotide polymorphism scanTM kit to investigate the relationship between susceptibility to rheumatoid arthritis (RA) and HLA-DPB1 rs9277535 polymorphism in 805 RA patients and 1095 healthy controls from the Chinese Han population." (PMID 33875616, 2021). "In the case of rheumatoid arthritis (RA), the HLA-DRB1, HLA-A, HLA-B, and HLA-DPB1 genes constitute genetic susceptibility for the development of the disease." (PMID 36981837, 2023). "For example, human susceptibility to rheumatoid arthritis (RA) was found linked strongly with certain MHC class I and II alleles, including HLA-DRB1, HLA-DPB1 and HLA-B." (PMID 31720104, 2019).
breast carcinoma (12 papers, 2009 to 2024). "Radiogenomic analysis identified 297 DEGs, including CXCL9, CCL18, and HLA-DPB1 which are known to be associated with breast cancer prognosis or angiogenesis." (PMID 38745321, 2024). "We then used machine learning methods to perform feature selection and reduction, which generated a clinical-friendly scoring system consisting of 5 genes (C3, CD27, GFPT2, GMFG, and HLA-DPB1) that could be used to predict clinical outcomes in breast cancer patients." (PMID 37287069, 2023). "The mRNA expression showed that all five genes were differentially expressed in breast cancer: C3, GFPT, and GMFG were significantly down-regulated, while CD27 and HLA-DPB1 were significantly up-regulated." (PMID 37287069, 2023). "HLA-DPB1 can be an antitumor factor to recruit NK cells, CD8+ T cells, and tumor-infiltrating lymphocytes such as Th1 and Tfh into breast cancer." (PMID 36245844, 2022).
acute GVHD (11 papers, 2016 to 2023). "Previously, we have shown in patients transplanted with a 10/10-MUD with a HLA-DPB1 mismatch that HLA-DPB1 mismatches that resulted in a positive PIRCHE score had a higher risk for acute GVHD than those HLA-DPB1 mismatches with a PIRCHE score of zero." (PMID 31068946, 2019). "The HLA non-coding SNPs have been associated with disease and regulation of infection such as the SNP in the 3′UTR of HLA-C associated to plasma HIV copy number and the SNP in the 3′UTR of HLA-DPB1 associated to acute GVHD." (PMID 30337930, 2018). "When donors with low-expression HLA-DPB1 molecules, recipients with mismatched high-expression HLA-DPB1 had a higher risk of acute GVHD (II-IV), compared with patients with low-expression HLA-DPB1 mismatches." (PMID 28206973, 2017). "Conversely, matched HLA-DPB1 was significantly associated with decreased incidence of acute GVHD (II-IV) (P < .001) and GVHD (III-IV) (P = .023)." (PMID 28206973, 2017). "In HSCT, the risk of acute GVHD was higher for recipients with rs9277534G-linked HLA-DPB1 mismatches than for recipients with rs9277534A-linked HLA-DPB1." (PMID 27798706, 2016). "Likewise, high expression of HLA class II (HLA-DPB1) antigens is reported to be risk factor for developing acute graft versus host disease in HSCT." (PMID 35666741, 2022). "The effect of individual HLA mismatches was replicated for acute GVHD (II-IV), with substantial heterogeneity in the analysis of HLA-DPB1 locus (I2 = 63.9%)." (PMID 28206973, 2017). "Specific HLA-DPB1 MMs with higher potential for T cell allorecognition, as well as expression levels of HLA-DPB1 variants, have been reported to be associated with acute GVHD in unrelated HSCT." (PMID 28018351, 2016). "They did find a link between MICA mismatches and grade II–IV acute GVHD but in univariate analysis only; this link was reenforced in patients with mismatches at both MICA and HLA-DPB1 who had a significantly greater risk to develop grade II to IV acute GVHD (HR = 2.51; 95% CI: 1.30–4.87; P < 0.01)." (PMID 28396673, 2017). "For example, high expression alleles of HLA-DPB1 were reported to be a risk effect for acute GVHD (see also above), and therefore, reducing their expression levels prior to transplantation might help to reduce the risk of developing acute GVHD." (PMID 32547543, 2020). "We failed to reveal possible sources of heterogeneity for TRM at HLA-DPB1 locus, and for chronic GVHD and acute GVHD (III-IV) at HLA-C locus." (PMID 28206973, 2017). "Among patients with 10/10 HLA matching, nonpermissive HLA-DPB1 mismatches were associated with a significantly increased risk of acute GVHD (III-IV) (P < .001), and had a trend of slight increasing risk of acute GVHD (II-IV) (P = .101)." (PMID 28206973, 2017).
asthma (11 papers, 2011 to 2026). "The same markers are present at lowest frequency in SPC compared with SPA, B and D. SPB is distinguished by high frequency of the rs987870 SNP, which present in the HLA-DPB1 gene and is associated with pediatric asthma in different Asian populations." (PMID 24223962, 2013). "SNP rs987870, located between HLA-DPA1 and HLA-DPB1, was consistently associated with pediatric asthma in 3 independent populations (Pcombined = 2.3×10−10, odds ratio [OR] = 1.40)." (PMID 21814517, 2011). "For example, HLA-DRB and HLA-DPB1 showed a correlation with aspirin-induced asthma." (PMID 38137494, 2023). "HLA-DPB1 has a strong link with asthma, ATA, AERD and inflammation." (PMID 25372592, 2014). "Analysis of asthmatic GWAS showed differential inflammatory genes (e.g., HLA-DPB1, HLA-DQA1, FCER1A), which verified the inflammation levels of asthma model." (PMID 36439114, 2022). "The genes of HLA-DRB5, HLA-DQA1, HLA-DPB1, CTSW, PSMB9, and TAP2 have the most number of edges with both predicted genes and childhood-onset asthma-related genes." (PMID 32867763, 2020). "Gene ontology and Kyoto Encyclopedia of Genes and Genomes analyses showed that the differentially expressed genes, HLA-DMB, IL4, HLA-DPB1, and CD40LG, were related to the occurrence of asthma, and HLA-DMB expression was significantly reduced in allergic asthma." (PMID 34714718, 2021).
hepatitis B (11 papers, 2012 to 2025). "The allele group HLA‐DPB1*13 and allele HLA‐DPB1*13:01 also showed a suggestive risk effect in our cohort, consistent with its reported involvement in susceptibility to other infections, such as Hepatitis B." (PMID 41314220, 2025). "For HLA‐DP, investigations in hepatitis B suggested a role for the expression levels of different allotypes defined by the presence of a polymorphism in the HLA‐DPB1 3′ untranslated region (UTR; rs9277534 G/A) in immune responses." (PMID 41365672, 2025). "We performed trans-ethnic association analyses of HLA-DPA1, HLA-DPB1 alleles and haplotypes with hepatitis B virus infection and disease progression among Asian populations comprising Japanese, Korean, Hong Kong, and Thai subjects." (PMID 24520320, 2014). "Conversely the HLA-DPB1 gene has been associated with several complex diseases such as pulmonary hypertension, hepatitis B infection and systemic sclerosis." (PMID 23029284, 2012). "Moreover, two SNPs in the 3′UTR region of HLA-DPB1, rs9277534 and rs9277535, were associated with hepatitis B viral clearance in those of European-American or African-American ancestry, as well as Asians." (PMID 33308178, 2020). "The association between HLA-DPB1 and ESRD has never been reported in Indonesia, but some studies in Indonesia stated that HLA-DPB1 is associated with hepatitis B infection susceptibility." (PMID 34671491, 2021).